EGFR (epidermal growth factor receptor)
Diseases named in the same sentence as EGFR in open-access papers (continued):
Sharing a sentence is not in itself a finding about the gene and the disease.
lung cancer (continued). "Cellular metabolism also plays a role in regulating the sensitivity and resistance of lung cancer cells to the EGFR-TKIs." (PMID 40940888, 2025). "Having established the role of PYCR1 in lung cancer progression, we investigated its potential as a therapeutic target against EGFR- and TLR-induced tumor formation." (PMID 41254241, 2025). "LMs occur in 3%–5% of patients with non‐small cell lung cancer (NSCLC), and this rate increases to 9% in patients with epidermal growth factor receptor (EGFR) mutations." (PMID 40484812, 2025). "The strength of this study lies in its focus on TLS formation and the tumor microenvironment in EGFR-mutant lung cancer, providing valuable insights into this specific subtype of the disease." (PMID 40723259, 2025). "The drug resistance of the third‐generation EGFR‐TKI osimertinib is a global problem in lung cancer therapy, we then studied the therapeutic potential of GM‐protac in osimertinib‐resistant lung cancer mice." (PMID 40842076, 2025). "Another study had revealed that silencing NSUN2 in lung cancer led to significant downregulation of EGFR expression." (PMID 40156167, 2025). "In patients with EGFR T790M–positive lung cancer who developed acquired resistance to osimertinib, EGFR amplification was observed in those with a retained T790M mutation (9/19, 47.4%)." (PMID 40310364, 2025). "Several ongoing T-cell engager studies in lung cancer include a variety of tumor-cell targets (e.g., EpCAM, B7-H6, Glypican-3, EGFR, among others), often with the T-cell engagement mechanism involving CD3 binding on the T-cell surface." (PMID 41479781, 2025). "A pfeRNA that interacts with the epidermal growth factor receptor (EGFR) and affects cell growth and colony formation in lung cancer H226 cells was mentioned in a publication." (PMID 40725121, 2025). "Specifically, in the field of lung cancer, this catalog advocates the inclusion of PD-L1, EGFR, ALK, ROS-1, KRAS, NTKR, RET, and MET." (PMID 40261489, 2025). "Gene modification through the introduction of various genes is valuable for studying the pathogenesis, metastasis, and drug resistance mechanisms of lung cancer, as well as for evaluating the efficacy of targeted therapies like EGFR and KRAS inhibitors." (PMID 40387186, 2025). "EGFR overexpression was observed in a variety of human solid tumors, such as kidney, pancreas, breast, ovary, bladder, colorectal, head and neck and lung cancers." (PMID 39940134, 2025). "EGFR emerged as the most frequently altered gene, consistent with patterns observed in Asian lung cancer patients, with a prevalence of 25.2 %." (PMID 40503459, 2025). "The standard treatment for EGFR-positive lung cancer is an EGFR tyrosine kinase inhibitor (TKI), with one study showing a progression-free survival (PFS) of 18.9 months and overall survival (OS) of 38.6 months." (PMID 40104434, 2025). "Using scRNA-seq in clinical lung cancer tissue samples and EGFR-TKI-resistant cell models, they found that upregulation of CD74 inhibited apoptosis and induced acquired resistance to osimertinib, facilitating tumor regeneration." (PMID 40003951, 2025). "Patients suffering from both TB and lung cancer must be aware of the interaction between anti‐tuberculosis medications and EGFR‐TKIs, such as Osimertinib." (PMID 40347011, 2025). "The cohort included 11 patients with neuroendocrine-transformed EGFR-mutant lung cancer and one patient with de novoEGFR-mutant SCLC." (PMID 41256964, 2025). "In lung cancer, PTMs orchestrate critical pathological processes, such as EGFR phosphorylation-driven proliferation, H3K27me3-mediated epigenetic silencing, and KEAP1 succinylation-regulated redox homeostasis." (PMID 41306527, 2025). "Epidermal growth factor receptor (EGFR) tyrosine kinase inhibitors (TKIs) are used in the treatment of non‐small cell lung cancer (NSCLC)." (PMID 40650440, 2025).
lung cancer (continued). "In 2025, researchers combined a biobank of patient-derived EGFR-mutant lung cancer organoids (ELCOL) with single-cell RNA-seq and complementary multi-omic analyses to delineate the mechanisms driving histologic transformation." (PMID 41425254, 2025). "Approximately 80% of exosomes isolated from lung cancer samples contain EGFR, in stark contrast to only about 2% of exosomes from samples of chronic lung inflammation." (PMID 40575159, 2025). "Epidermal growth factor receptor (EGFR) tyrosine kinase inhibitors (TKI) are widely used in the treatment of advanced non‐small cell lung cancer (NSCLC)." (PMID 40650440, 2025). "Research has demonstrated that inhibiting the EGFR oncogene activates the NF-κB signaling pathway in lung cancer, subsequently increasing the expression of the apolipoprotein B mRNA-editing catalytic polypeptide-like (APOBEC) enzyme APOBEC3B (A3B)." (PMID 40003951, 2025). "This genetic alteration is frequently found in lung cancers and is known to sensitize the cells towards EGFR inhibitors indicating dependency of the carrier cells towards ligands to this receptor." (PMID 40806483, 2025). "The expression of MIG-6 has been demonstrated to be suppressed in nonsmall-cell lung cancer tissues and liver cancer, leading to increased EGFR/AKT signaling and enhanced cell proliferation and metastasis 8,19." (PMID 40535815, 2025). "The discovery of EGFR tyrosine kinase inhibitors (TKIs) was important in the field of lung cancer treatment." (PMID 39907159, 2025). "Recent innovations such as osimertinib and sunvozertinib have further extended survival in EGFR-mutant lung cancer; improved CNS penetration has translated into better control of brain and leptomeningeal metastases." (PMID 41008908, 2025). "PIK3CA mutations can promote cellular survival and proliferation, which contribute to resistance to EGFR-TKIs in lung cancer." (PMID 41189942, 2025). "EGFR pathway activation is also associated with tumour-promoting inflammatory cytokines and increased markers of T cell exhaustion in EGFR-driven mouse models of lung cancer." (PMID 40647497, 2025). "The MARIPOSA trial compared the combination of amivantamab plus lazertinib, a third-generation EGFR TKI, to osimertinib in untreated patients with lung cancer expressing either Del19- or L858R-EGFR." (PMID 40243603, 2025). "To assess the impact of A3A and A3B upregulation on the response of lung cancer cells to EGFR inhibition, we used CRISPR/Cas9 to knock out each gene in PC9 cells." (PMID 40323013, 2025). "The epidermal growth factor receptor mutant (EGFRm) non‐small cell lung cancer (NSCLC) has a unique “cold” immune profile." (PMID 39994841, 2025). "That study demonstrated the significant advantages of using 3D lung cancer cell cultures, specifically spheroid models, over traditional 2D cultures in proving the efficacy of TKIs targeting EGFR signaling." (PMID 39790707, 2025). "One such pathway is the EGFR signaling pathway, which is frequently dysregulated in various cancers, including lung cancer." (PMID 40210802, 2025). "Initially, the TKI treatment was broadly applied in NSCLC, but in recent years, the use has been limited mostly to EGFR mutant lung cancers." (PMID 40650440, 2025). "The gaining effect of ginsenoside Rg3 on EGFR-TKI combination in anti-lung-cancer therapy was fully demonstrated, and a sequential dosing regimen that was more effective than the concurrent dosing regimen was proposed." (PMID 40732366, 2025). "This study gathered insight on the diagnosis and treatment of advanced EGFR‐mutant NSCLC from a panel of lung cancer experts in Asia, where the lung cancer burden is high." (PMID 40515576, 2025). "In lung cancer, particularly non-small cell lung cancer (NSCLC), oncogenic alterations such as mutations in KRAS, EGFR, BRAF, and ALK rearrangements activate key signaling cascades, most notably the RAS–RAF–MEK–ERK and PI3K-AKT–mTOR pathways." (PMID 40823246, 2025).
lung cancer (continued). "The rise of first‐generation EGFR inhibitors, Gefitinib and Erlotinib, transformed lung cancer care." (PMID 40720248, 2025). "As a result, treating lung cancer with apigenin and gefitinib together offers an appealing alternative therapeutic option for acquired resistance to epidermal growth factor receptor TKIs." (PMID 40728967, 2025). "Next, to evaluate the predictive value of the supercluster signatures for therapy response, we analyzed a dataset comprising pre-treatment tumor samples from eight patients with EGFR-mutant lung cancer treated with the tyrosine kinase inhibitor Osimertinib." (PMID 41019980, 2025). "All four lung cancer cells consistently expressed the EGFR, but the levels of EGFR phosphorylated at Tyr1068/1092 and Tyr1173/1197 varied between cell types." (PMID 40365309, 2025). "We also found that both Lac and DT were effective in shrinking lung cancers in bone marrow reconstructed in EGFR-DEL mice." (PMID 39979425, 2025). "We developed a novel DNA damage repair (DDR)‐based prognostic model for EGFR‐mutant non‐small cell lung cancer (NSCLC)." (PMID 39994841, 2025). "Similar findings have been observed in some lung cancer patients progressing on first- or third-generation EGFR-TKIs or crizotinib." (PMID 41268440, 2025). "This case demonstrates the remarkable efficacy of ACTL cellular immunotherapy in advanced lung cancer patients with EGFR-TKI acquired resistance, providing new treatment insights for similar refractory cases." (PMID 40959071, 2025). "Several exosomal membrane protein markers, including EGFR, CD91, and CD317, have been identified as potential diagnostic biomarkers for lung cancer." (PMID 41573685, 2025). "This study introduces an innovative approach utilizing folic acid-modified milk exosomes loaded with c-kit siRNA (FA-mExo-siRNA-c-kit) to target EGFR-TKI resistance in lung cancer." (PMID 39744423, 2025). "Current targeted therapies are primarily based on a small panel of gene mutations like EGFR and ALK, which are detectable in a small proportion of lung cancer patients in the clinic." (PMID 40655139, 2025). "The development of resistance to epidermal growth factor receptor (EGFR) tyrosine kinase inhibitor (TKI) treatment represents a significant challenge to targeted therapies for lung cancer." (PMID 41310903, 2025). "In any case, since it has been reported that distant recurrence is generally more common in EGFR-mutant lung cancer than in wild-typed tumors, and it would be of great interest to see what the long-term results of the LAURA trial will bring in the future." (PMID 39910007, 2025). "The EGFR exon 19 deletions in lung cancer were substantially greater than wild-type EGFR, and the RP11-325I22.2 was most markedly elevated." (PMID 39912974, 2025). "One of these proteins is epidermal growth factor receptor (EGFR), which is found in about 80% of exosomes isolated from lung cancer patients and can be detected in early stages of the disease." (PMID 41227214, 2025). "Gefitinib and osimertinib, the first-generation and third-generation EGFR-TKI, have shown promising results in patients with EGFR-mutated lung cancer in clinical treatment." (PMID 42004224, 2025). "Sustained over-activation of EGFR in lung cancer increases the expression of EMT-inducing factors thereby favoring lung cancer metastasis." (PMID 41254689, 2025). "This process ultimately established a positive feedback loop that sustains lung cancer resistance to EGFR-TKI." (PMID 40264038, 2025).
lung cancer (continued). "Reducing the expression of CD55 and CD59, which EGFR heightens, can trigger the complement system and enhance lung cancer sensitivity to checkpoint inhibitors." (PMID 40515636, 2025). "This synergetic interplay helps to extend the scale of effectiveness in individuals battling lung cancer using EGFR-TKI treatment." (PMID 40417000, 2025). "ABT-737 was also used in EGFR-mutant lung cancer cells and was found to potentiate the apoptotic effect of gefitinib and erlotinib." (PMID 40940888, 2025). "Discovery and drug development of new lung cancer‐related targets: EGFR, ALK, ROS1, RET, MET, BRAF inhibitors, etc." (PMID 40135802, 2025). "It has been shown that the downregulation of AXL in lung cancer cells resistant to EGFR TKIs reverts the EMT process and sensitizes the cells to tyrosine kinase inhibitors." (PMID 40243603, 2025). "Chemotherapy, typically platinum-etoposide, is the backbone of treatment of neuroendocrine-transformed EGFR-mutant lung cancer." (PMID 41256964, 2025). "This study further supports the therapeutic potential of furmonertinib in rare EGFR-mutant lung cancer." (PMID 40963567, 2025). "In recent years, with the rapid advancement of precision diagnosis and treatment for lung cancer, EGFR-TKIs have become the standard treatment for patients with EGFR-mutated advanced NSCLC." (PMID 41257744, 2025). "In the research on lung cancer, CD200+ CAFs can increase the sensitivity of epidermal growth factor receptor (EGFR) gene mutation-positive lung cancer cells to gefitinib." (PMID 40626005, 2025). "c-Src is directly involved in tyrosine phosphorylation at this same site in Vav242 and both proteins co-localize with EGFR, a known driver of lung cancer." (PMID 39764007, 2025). "Tobacco-related signature is tied to poor lung cancer outcomes and reduced EGFR-targeted therapy efficacy." (PMID 40808963, 2025). "Over the past 31 years, the FDA has approved 20 small molecules and two monoclonal antibodies for the treatment of lung cancer, most of which are classified as EGFR and ALK inhibitors." (PMID 39940833, 2025). "The development of tyrosine kinase inhibitors (TKIs) for late-stage epidermal growth factor receptor (EGFR)-mutant non-small cell lung cancer (NSCLC) represented a drastic change in the treatment of late-stage lung cancer." (PMID 40076686, 2025). "Clinical testing guidelines provide guidance for the standard of care for molecular testing in lung cancer, and EGFR testing is a requirement for patients with advanced-stage LUAD, that is, stage IB or higher." (PMID 40634781, 2025). "Advanced‐stage EGFR‐mutated lung non‐small cell lung cancer (NSCLC) challenges current treatment paradigms, particularly after frontline EGFR‐TKI therapy failure." (PMID 40289745, 2025). "Exosomal components, including proteins such as EGFR, LRP1, and LG3BP, as well as RNAs present in the serum and urine of lung cancer patients, have been associated with the stage and metastasis of the disease." (PMID 41573685, 2025). "BPA upregulates matrix metalloproteinase-2 and −9 (MMPs) through GPER, not ER, and also induces activation of extracellular signal-regulated kinases (ERK) 1 and 2 through GPER/epidermal growth factor receptor (EGFR) in lung cancer cells." (PMID 40116906, 2025). "The study objective was to investigate EGFR-TKI response in wild-type EGFR lung cancer cells that varied in BRG1 status." (PMID 41514577, 2025). "EGFR inhibitors have been clinically used to treat malignancies including breast, colon and lung cancer." (PMID 40098972, 2025). "Our previous study showed that afatinib, a clinically available EGFR-TKI for lung cancer therapy, attenuated oxygen-glucose deprivation (OGD)-induced neuroinflammation in primary cultured astrocytes." (PMID 40444141, 2025).
lung cancer (continued). "Antigens such as Melanoma-associated antigen A1 (MAGE-A1), MAGE-A3, Mucin 1 (MUC1), New York esophageal squamous cell carcinoma 1 (NY-ESO-1) and Epidermal growth factor receptor (EGFR) are some of the main TAAs that use in clinical trials in lung cancer." (PMID 40625850, 2025). "In our setting, EGFR testing was the most common molecular test done for lung cancer with a positive rate like that reported in Asian communities." (PMID 40112503, 2025). "In non‐small cell lung cancer (NSCLC), several genetic mutations influencing therapy choices have been identified, including mutations in EGFR, ALK, ROS1, and BRAF." (PMID 39947926, 2025). "If EGFR L861R is detected, afatinib or osimertinib should be considered as the recommended treatment options for patients with EGFR L861R–positive lung cancer." (PMID 41350121, 2025). "The identification of epidermal growth factor receptor (EGFR) overexpression in lung cancer led to the creation of CIMAvax-EGF." (PMID 40922740, 2025). "The Solo‐test Driver panel has the potential to identify an additional 18.3%, 16.5%, and 8.7% of RAS+ colorectal, PIK3CA+ breast, and EGFR+ lung cancer patients, respectively, when compared to FDA‐approved PCR tests." (PMID 40056420, 2025). "A striking example is the combination of the chemotherapy pemetrexed (PEM) with the EGFR TKI osimertinib in EGFR-mutant lung cancer." (PMID 41295218, 2025). "This evidence let us confirm SMARCB1 as a tumor suppressor in lung cancer and prompted us to investigate lung cancer progression and response to the EGFR-TKI-afatinib at in vivo (nu-/nu-) mice model." (PMID 39971779, 2025). "Previous studies on lung cancer and EGFR mutation primarily concentrated on lung adenocarcinoma (LUAD), as the incidence of EGFR mutation in LUAD was notably the highest." (PMID 40969259, 2025). "Studies in EGFR mutant lung cancer show that sub-populations with MET amplification-induced activation of PI3K/AKT signaling possess resistance to EGFR kinase inhibitors prior to therapy." (PMID 39941808, 2025). "This is due to lung cancer’s predilection for amplification of the EGFR gene, as well as the fact that several treatments for NSCLC inhibit EGFR." (PMID 40283044, 2025). "Non–small cell lung cancer (NSCLC) accounts for 85% of all lung cancers and over 60% express wild-type EGFR (WT-EGFR); however, EGFR tyrosine kinase inhibitors (TKIs) have limited effect in most patients with WT-EGFR tumors." (PMID 39859343, 2025). "We identified 80 targeted proteins involved in lung cancer, with EGFR being the most enriched in pathway enrichment analysis." (PMID 41155483, 2025). "A notable example is lung cancer, where, after treatment with EGFR-targeted tyrosine kinase inhibitors (TKIs), some clones become highly resistant to TKIs, poised for proliferation when given the opportunity." (PMID 40183077, 2025). "A pre-clinical study demonstrated that in EGFR mutant lung cancer cells, TKI-resistant cells exhibit sensitivity to PARP inhibitors, potentially mediated by NOX-dependent reactive oxygen species." (PMID 40182045, 2025). "According to a previous study, lung cancer EGFR exon 19 deletions resulted in aberrant expression of several lincRNAs." (PMID 39912974, 2025). "It is worth mentioning that the biological finding reflects a pioneering effort in demonstrating an anticancer potential of STX, evidenced by its capacity in inducing apoptosis and mitigating EGFR expression in NSC lung cancer." (PMID 40329373, 2025). "EGFR is a major driver in lung cancer, regulating important tumorigenic processes such as proliferation, apoptosis, angiogenesis, and invasion." (PMID 39578555, 2025).